CGREF1 (cell growth regulator with EF-hand domain 1)
Description:
Mediates cell-cell adhesion in a calcium-dependent manner (By similarity). Able to inhibit growth in several cell lines.
Synonyms: CGR11
Tractability: Antibody: UniProt places it where antibodies can reach, with medium confidence; UniProt predicts a signal peptide or a membrane-spanning region; its Gene Ontology location is reachable by antibodies, with medium confidence.
Gene: Protein-coding gene on chromosome 2 (27,098,889 to 27,119,128, reverse strand). Ensembl gene ENSG00000138028.
Subcellular location: Secreted
Subcellular location (Human Protein Atlas): Golgi apparatus; Predicted to be secreted
Gene Ontology:
Molecular function: protein binding; calcium ion binding
Biological process: negative regulation of cell population proliferation
Cellular component: extracellular region
Genetic constraint (gnomAD): Loss-of-function variants: 16 observed, 17.81 expected, observed/expected ratio (o/e) 0.9, 90% interval 0.61 to 1.36. The upper end of that interval is the gene's LOEUF score, 1.36, which puts it in group 5 of 6, group 1 being the genes least tolerant of losing a copy. Missense variants: 296 observed, 377 expected, observed/expected ratio (o/e) 0.79, 90% interval 0.71 to 0.86. Synonymous variants: 142 observed, 153.74 expected, observed/expected ratio (o/e) 0.92, 90% interval 0.81 to 1.06.
Homologues: Orthologues: chimpanzee CGREF1 (98% identical), macaque CGREF1 (79% identical), dog CGREF1 (59% identical), guinea pig CGREF1 (58% identical), mouse Cgref1 (57% identical), rabbit CGREF1 (57% identical), rat Cgref1 (57% identical), Caenorhabditis elegans F55A11.1 (12% identical), Drosophila melanogaster CG17271 (11% identical), Caenorhabditis elegans C29E4.14 (10% identical), Caenorhabditis elegans T04F3.4 (9% identical). Paralogues in human: MCFD2 (13% identical).
Diseases named in the same sentence as CGREF1 in open-access papers:
CGREF1 is named in the same sentence as 34 diseases in open-access papers, as found by Europe PMC text mining. Sharing a sentence is not in itself a finding about the gene and the disease. The quoted sentences say what the papers report.
osteosarcoma (5 papers, 2023 to 2025). A usually aggressive malignant bone-forming mesenchymal neoplasm, predominantly affecting adolescents and young adults. "Our analysis of public databases and clinical samples revealed that CGREF1 is highly expressed in osteosarcoma and is associated with poor prognosis." (PMID 39707194, 2024). "In patients with osteosarcoma, elevated expression of CGREF1 is associated with a higher degree of malignancy and poor prognosis." (PMID 39707194, 2024). "The expression of CGREF1 was significantly upregulated in osteosarcoma and correlated with unfavorable prognosis." (PMID 39707194, 2024). "CGREF1 exerted a regulatory effect on the proliferation of osteosarcoma cells both in vitro and in vivo through modulation of the wnt/β-catenin signaling pathway." (PMID 39707194, 2024). "Subsequently, different osteosarcoma cell lines were screened for their CGREF1 expression levels, and two cell lines, namely 143B and MG63, exhibiting relatively high CGREF1 expression were selected for subsequent experiments." (PMID 39707194, 2024). "The CCK8 results from the CGREF1 cell line were consistent with those obtained after siRNA transfection, suggesting weakened proliferation ability of osteosarcoma cells upon CGREF1 knockdown." (PMID 39707194, 2024). "In this study, we have identified the oncogenic role of CGREF1 in osteosarcoma and investigated its involvement and potential molecular mechanisms in the malignant biological behaviors of osteosarcoma cells through both in vivo and in vitro experiments." (PMID 39707194, 2024). "Knockdown of CGREF1 impeded cell cycle progression and suppressed the proliferation of osteosarcoma cells." (PMID 39707194, 2024). "The results of CCK8 and plate cloning showed that CGREF1 knockdown decreased the proliferation ability of osteosarcoma cells." (PMID 39707194, 2024). "In this study, analysis of TCGA patient data revealed a significant correlation between high expression levels of CGREF1 and poor prognosis in osteosarcoma patients." (PMID 39707194, 2024). "The results of CCK8 and plate cloning showed that overexpression of CGREF1 enhanced the proliferation of osteosarcoma cells." (PMID 39707194, 2024). "CCK8 experiments following siRNA transfection demonstrated a reduction in osteosarcoma cell proliferation at lower levels of CGREF1 knockdown, directly proportional to the extent of knockdown." (PMID 39707194, 2024). "Overall, these findings suggest that elevated levels of CGREF1 enhance Cyclin D expression, accelerate cell cycle progression, and augment proliferative capacity in osteosarcoma cells." (PMID 39707194, 2024). "At the same time, we used wnt signaling pathway inhibitors in osteosarcoma cell lines overexpressing CGREF1 to perform overexpressed gene restoration experiments." (PMID 39707194, 2024). "Subsequently, we manipulated the gene expression of CGREF1 in osteosarcoma cell lines and conducted comprehensive in vitro functional experiments." (PMID 39707194, 2024). "Mechanistically, CGREF1 enhances Cyclin D expression by modulating GSK3β/β-catenin signaling within the Wnt pathway, thereby promoting the transition of osteosarcoma cells from G1/G0 to S phase and facilitating their proliferation." (PMID 39707194, 2024). "We subsequently conducted western blot analysis on 12 osteosarcoma samples and observed a significant upregulation of CGREF1 protein levels in osteosarcoma tissues compared to corresponding non-tumor tissues." (PMID 39707194, 2024). "To explore the underlying molecular mechanism by which CGREF1 exerts its inhibitory effect on osteosarcoma cell proliferation, we performed RNA-Seq analysis following CGREF1 knockdown in 143B cells." (PMID 39707194, 2024). "In the future, targeting CGREF1 could potentially offer a novel therapeutic strategy for treating osteosarcoma." (PMID 39707194, 2024).
osteosarcoma (continued). "Our findings demonstrate that CGREF1 exerts regulatory control over the activation level of the Wnt pathway by modulating GSK3β/β-catenin signal transduction within this pathway, thereby influencing the malignant proliferative behavior of osteosarcoma cells." (PMID 39707194, 2024). "Moreover, the wnt reversion experiment further substantiated that CGREF1 modulated osteosarcoma cell proliferation through regulation of GSK3β/β-catenin signaling within the wnt pathway." (PMID 39707194, 2024). "In short, CGREF1 enhances tumor formation and growth of osteosarcoma in vivo." (PMID 39707194, 2024). "However, knockdown of CGREF1 resulted in decreased Cyclin D expression, leading to inhibition of cell cycle progression and subsequent suppression of proliferation in osteosarcoma cells." (PMID 39707194, 2024). "Additionally, western blot analysis confirmed the elevated expression of CGREF1 in osteosarcoma samples." (PMID 39707194, 2024). "Collectively, these findings suggest that CGREF1 exerts an influence on Cyclin D expression through the regulation of GSK3β/β catenin signaling in the wnt pathway, thereby modulating the malignant proliferation of osteosarcoma cells." (PMID 39707194, 2024). "Moreover, CCK8 assay revealed an augmented proliferation rate of osteosarcoma cells following CGREF1 overexpression." (PMID 39707194, 2024). "In the present study, we demonstrated that knockdown of CGREF1 resulted in inhibition of GSK3β phosphorylation, reduction in β-catenin protein levels, and suppression of downstream Cyclin D activation by β-catenin, consequently leading to impaired proliferation ability of osteosarcoma cells." (PMID 39707194, 2024). "Consequently, targeting CGREF1 may hold promise as a novel therapeutic approach for clinical management of osteosarcoma." (PMID 39707194, 2024). "Consequently, simultaneous targeting of both CGREF1 and the Wnt signaling pathways may offer novel therapeutic strategies for treating individuals with osteosarcoma." (PMID 39707194, 2024). "Given the high expression of CGREF1 in osteosarcoma cell lines 143B and MG63, we designed three siRNAs targeting CGREF1 for transfection into these cell lines, followed by assessment of knockdown efficiency using western blot analysis." (PMID 39707194, 2024). "Further experimental results demonstrated that CGREF1 affects activation of the Wnt pathway by regulating GSK3/β-catenin signaling, thereby affecting proliferation ability of osteosarcoma cells." (PMID 39707194, 2024). "Cell scratch migration and Transwell invasion experiments demonstrated no significant impact on migration and invasion abilities upon CGREF1 knockdown in both 143B and MG63 osteosarcoma cells." (PMID 39707194, 2024). "We demonstrated the results by IHC experiments, and observed that CGREF1, CORT and RHBDL2 proteins expression were high in the tissue of osteosarcoma patients, while the proteins were lowly expressed in normal tissue." (PMID 37441535, 2023). "Our findings demonstrated that CGREF1 did not directly influence the migration and invasion capabilities of osteosarcoma cells." (PMID 39707194, 2024). "Several of these genes have been studied in osteosarcoma including ANGPT1 upregulation associated with nonmetastatic disease and CGREF1 overexpression linked to a poor prognosis." (PMID 39701601, 2024). "However, no substantial impact on migration and invasion ability of osteosarcoma cells was observed after the overexpression of CGREF1 as determined by cell scratch migration and Transwell invasion experiments." (PMID 39707194, 2024). "The role of CGREF1 in the development of osteosarcoma and its mechanism have not been reported." (PMID 39707194, 2024). "Furthermore, a disease‐free survival (DFS) predictor model of osteosarcoma, including ZNF720, REEP3, CNNM2, and CGREF1, can be created using TARGET datasets, demonstrating that a combination of multiple genes may be responsible for cisplatin resistance." (PMID 36408691, 2023).
hepatoma (3 papers, 2022 to 2025). "Consistently, in hepatoma cell line Huh7, the production of human homolog CGREF1 increased upon overexpression of CREB-H-FL and CREB-H-ΔTC, of which the induction by CREB-H-ΔTC was more pronounced." (PMID 40303310, 2025). "Second, the transfection of CREB-H-FL, ΔTC or Cgref1/CGREF1 in hepatoma cell lines enabled the detection of Cgref1/CGREF1 protein in the cell culture media." (PMID 40303310, 2025). "It has been evaluated that PCNP shows mRNA transcription level similarity with CGREF1 in the regulation of the hepatoma cell cycle in the zebrafish hepatoma model." (PMID 35186732, 2022). "Thus, to see if CREB-H activates the transcriptional activity of the Cgref1 promoter, we performed dual-luciferase reporter assay using mouse hepatoma cell line Hepa1-6." (PMID 40303310, 2025).
cervical cancer (2 papers, 2022 to 2024). A primary or metastatic malignant neoplasm involving the cervix. "In contrast, in cervical cancer studies, nicotinamide adenine dinucleotide (NAD+) metabolic models have shown that high expression of CGREF1 is associated with poor prognosis." (PMID 39707194, 2024).
Hyperglycemia (2 papers, 2022 to 2025). An increased concentration of glucose in the blood. "Cgref1-/-mice showed lower tendencies of developing obesity, hyperglycaemia and dyslipidaemia, associated with compromised hepatic de novo lipogenesis." (PMID 40303310, 2025). "Therefore, in short summary, an overall metabolically healthier phenotype including the reduced tendency of acquiring hyperglycemia and dyslipidemia in Cgref1-/- mice indicated that Cgref1 might be an underlying factor of metabolic disease pathogenesis." (PMID 40303310, 2025). "As phenotype analysis suggested the correlation of Cgref1 with hyperglycemia and undermined glucose homeostasis, we decided to compare insulin-mediated glucose uptake between WT and Cgref1-/- mice." (PMID 40303310, 2025).
Anxiety (1 paper, 2024). Intense feelings of nervousness, tension, or panic often arise in response to interpersonal stresses. "Four genes were associated with both treatment outcomes and these symptom dimensions: CGREF1 (anxiety); MCHR1 (neuroticism); FTO and NRXN3 (sleep)." (PMID 39191930, 2024).
autism (1 paper, 2025). Persistent deficits in social interaction and communication and interaction as well as a markedly restricted repertoire of activity and interest as well as repetitive patterns of behavior. "Finally, both schizophrenia and autism show evidence for association with PTVs in CGREF1." (PMID 40753099, 2025).
cardiomyopathy (1 paper, 2013). A disease of the heart muscle or myocardium proper. "From these tables, we found that gene clusters anchored by the major genes CGREF1, PMS1 and TNIK all had multiple genes in several cardiomyopathy-related pathways." (PMID 23879630, 2013).
colon cancer (1 paper, 2021). "CGREF1, a protein secreted in the classical secretory pathway from endoplasmic reticulum to Golgi, has been found to play an important role in regulating the transcriptional activity of AP-1 and the proliferation of human colon cancer cells, but the role of CGREF1 in other cancers is unclear." (PMID 34488541, 2021).
colorectal adenocarcinoma (1 paper, 2024). The most common type of colorectal carcinoma. "We initially investigated the levels of CGREF1 in various tumor types and observed a significant upregulation of CGREF1 expression in diverse tumors (including renal clear cell carcinoma, colorectal adenocarcinoma, rectal adenocarcinoma, etc.)compared to their respective non-tumor counterparts." (PMID 39707194, 2024).
colorectal cancer (1 paper, 2024). A primary or metastatic malignant neoplasm that affects the colon or rectum. "In a predictive model for overall survival of early-onset colorectal cancer, low CGREF1 expression was associated with poor prognosis." (PMID 39707194, 2024).
dementia (1 paper, 2025). Loss of intellectual abilities interfering with an individual's social and occupational functions. "Significantly associated proteins at a false discovery rate (FDR) < 0.05 in both models 1 and 2 were CGREF1, MET, ALDH2, NECTIN2, APOC1, APOE and FOSB for HFRS, and CDK and POF1B for HFRS without dementia." (PMID 40764432, 2025).
Insulin resistance (1 paper, 2025). Increased resistance towards insulin, that is, diminished effectiveness of insulin in reducing blood glucose levels. "We define CREB-H-dependent expression of Cgref1 and provide evidence that extracellular Cgref1 is largely retained in epididymal white adipose tissue (eWAT), whereby it causes insulin resistance locally and reduces glucose uptake." (PMID 40303310, 2025). "However, in circumstances where Cgref1 expression becomes excessive, eWAT develops insulin resistance, which in turn promotes hepatic glucose production, lipogenesis and MASLD development." (PMID 40303310, 2025).
lentivirus infection (1 paper, 2024). Virus diseases caused by the Lentivirus genus. "Subsequently, stable cell lines of 143B and MG63 with low CGREF1 expression were generated through lentivirus infection using the siCGREF1-1 sequence, and the efficiency of stable knockdown was confirmed to be low." (PMID 39707194, 2024).
liver diseases (1 paper, 2024). "MiR-212-3p and miR-155-5p may suppress the protective effects of CGREF1, leading to the deterioration of liver diseases like NAFLD, where maintaining hepatocyte integrity is crucial for preventing disease progression." (PMID 39683393, 2024).
liver fibrosis (1 paper, 2024). "By promoting cell growth and inhibiting unnecessary cell death, CGREF1 helps maintain liver tissue integrity after cholesterol-induced damage and encourages regeneration, preventing liver fibrosis or damage progression." (PMID 39683393, 2024).
lung carcinoma (1 paper, 2015). "A number of classifier genes that regulate cell growth and proliferation are up-regulated in patients with lung cancer, including SDC2, and NKX3-1 as well as the cell-cycle-arrest mediator CGREF1." (PMID 25944280, 2015).
neuroblastoma (1 paper, 2024). Neuroblastoma (NB) is the most common solid, extracranial childhood tumor. "In a study of neuroblastoma patients undergoing chemotherapy, CGREF1 has been identified as a novel somatic mutation during chemotherapy that is involved in mediating nerve cell growth and may be associated with chemotherapy resistance and poor prognosis in neuroblastoma patients." (PMID 39707194, 2024).
Obesity (1 paper, 2025). Accumulation of substantial excess body fat. "First of all, Cgref1-/- mice were less predisposed to obesity." (PMID 40303310, 2025). "Nonetheless, we are intrigued to see if Cgref1 may affect gene expression in different ATs relevant to adipocyte thermogenesis, an energy-expending and anti-obesity cellular mechanism." (PMID 40303310, 2025).
schizophrenia (1 paper, 2025). A major psychotic disorder characterized by abnormalities in the perception or expression of reality.
tumor (5 papers, 2020 to 2025). "IHC results demonstrated that the levels of Ki-67 and Cyclin D in tumor tissues were significantly reduced in the CGREF1 knockdown group compared to the control group, indicating a decrease in cell proliferation." (PMID 39707194, 2024). "With the rise of bioinformatics technology, researchers began to focus on the impact of CGREF1 on tumor disease." (PMID 39707194, 2024). "Finally, experiments using subcutaneous transplanted tumor models in nude mice showed that CGREF1 knockdown inhibited tumor growth in vivo by inhibiting the Wnt/β-catenin signaling pathway." (PMID 39707194, 2024). "Finally, we verified that the expression levels of KLF9, MCM2, INHBA, and CGREF1 were related to age, tumor stage, and differentiation and were closely related to the prognosis of young CRC patients." (PMID 37370046, 2023). "The results showed that knocking down CGREF1 could significantly inhibit tumor growth." (PMID 39707194, 2024). "This suggests that CGREF1 may have an impact not only on tumor cells themselves but also on other cells (such as neutrophils) within the tumor microenvironment through mechanisms like vesicle secretion and other pathways, which necessitates further exploration and investigation." (PMID 39707194, 2024). "In our study, the expression of KLF9, MCM2, INHBA, and CGREF1 was significantly correlated with TNM clinical stage and tumor differentiation, excluding tumor location, age, and sex." (PMID 37370046, 2023).
psychiatric disorder (1 paper, 2025). A disorder characterized by behavioral and/or psychological abnormalities, often accompanied by physical symptoms.
CGREF1 also shares sentences with these, for which no sentence is quoted: cancer (3 papers); prostate carcinoma (3); Hepatic steatosis (2); dyslipidaemia (1); dyslipidemia (1); gastric cancer (1); glioblastoma (1); Hypertension (1); liver cancer (1); metabolic disease (1); rectal adenocarcinoma (1); renal clear cell carcinoma (1); uterine cancer (1).